CRP (C-reactive protein)
Diseases named in the same sentence as CRP in open-access papers (continued):
Sharing a sentence is not in itself a finding about the gene and the disease.
Hypertension (continued). "After adjustment, hs-CRP and WBC remained modestly associated with high blood pressure in all participants; however, the effect of age ≥ 65 years on high BP was still the strongest among predictors." (PMID 38720047, 2024). "From a clinical point of view, the Ob-HTG group had a higher presence of hypertension and increased levels of hs-CRP and HbA1c and fatty liver and insulin resistance indexes." (PMID 36769659, 2023). "Previously, it was shown that hypertension with high homocysteine (HHcy) (H-type hypertension) and CRP can increase the incidence of ischemic stroke." (PMID 37051146, 2023). "Compared with patients with low sIL-2R levels, patients with high sIL-2R levels tended to be older and had significantly higher total cholesterol, fasting blood sugar, hs-CRP levels, and more often had hypertension, heart rate (>100 b.p.m)." (PMID 37139133, 2023). "And levels of weight, WC, BMI, WHtR, SBP, DBP, TG, TC, LDL-C, ApoB, uric acid, FPG, HbA1c and Hs-CRP were also higher in participants with new-onset hypertension (p < 0.05)." (PMID 38156282, 2023). "A large epidemiological study indicated the CRP rate as a mediator of these disorders since there elevated CRP was found in hypertension and periodontitis." (PMID 37568542, 2023). "Hypertension, type 1 and 2 diabetes, lower SES, lower kidney function, and higher CRP were each associated with a higher risk of PAD, similarly in both sexes." (PMID 37851596, 2023). "A logistic regression model adjusted for age, sex, smoking status, hypertension, history of any autommune disease and median CRP." (PMID 38028500, 2023). "Variables that remained unbalanced in the matched sample included length of stay, month of admission, smoking status, insurance status, hypertension status, systolic blood pressure, diastolic blood pressure, SpO2, ferritin, c-reactive protein, and D-Dimer." (PMID 36608047, 2023). "We detected significant mediating effect through hypertension (8.4%), HbA1c (7.0%), CRP (6.4%), HDL (5.2%) and high cholesterol (4.1%)." (PMID 36384749, 2023). "While the significance of these correlations was lost after adjustment for age, sex, BMI, and IL-6 or CRP, adjustment for age, sex, and statins as well as for age, sex, and hypertension made the correlation between EL and IDL-TG/IDL-apoB insignificant." (PMID 37445857, 2023). "These comprised indicators of poor glycaemic control (HbA1c 7.0%), adverse lipid profile (HDL 5.2%, high cholesterol 4.1%), hypertension (8.4%) and systemic inflammation (CRP 6.4%)." (PMID 36384749, 2023). "Patients with high serum cis-C levels are at the greatest risk of CVDs (even with mild renal dysfunction), and patients with very high serum cis-C levels usually have arterial hypertension, dyslipidemia, high BMI, and higher serum levels of C-reactive protein." (PMID 37239168, 2023). "Adjusted odds ratio (OR) and 95% confidence interval (CI) for severe CAD, high levels of lipid profile, high levels of q-CRP, and hypertension among the tertiles of DII (energy-adjusted)." (PMID 37841398, 2023). "A separate study revealed correlations between CRP and pulse pressure, systolic blood pressure, and hypertension." (PMID 37298077, 2023). "Multiple human and animal studies confirm the role of inflammation, as predicted by plasma CRP level, in the development of hypertension." (PMID 37298077, 2023). "The birth weight–MI effect was mediated through hypertension (8.4%), glycated haemoglobin (7.0%), C reactive protein (6.4%), high-density lipoprotein (5.2%) and high cholesterol (4.1%)." (PMID 36384749, 2023). "CRP levels, white blood cell counts and proinflammatory cytokines are recognised biomarkers for predicting risks of hypertension, cardiovascular and cardiometabolic conditions in large population-based studies." (PMID 37925459, 2023). "Most of the participants had a CRP level < 1 mg/L (1041; 47.47%), 188 (8.57%) had DM, 528 (24.08%) had hypertension and 40 (1.82%) had kidney disease." (PMID 36771478, 2023).
Hypertension (continued). "Univariate analysis identified age, male sex, hypertension, cardiovascular disease, dyslipidemia, cerebrovascular disease, urea, creatinine, AST, total bilirubin, LDH, albumin, procalcitonin, WBC, CRP, NLR and PAR as possible risk factors for ICU admission." (PMID 36950410, 2023). "The cardiometabolic improvements also reverted toward the baseline levels, including prediabetes (HbA1c), hyperlipidaemia, inflammation (CRP) and hypertension." (PMID 37047163, 2023). "Markers of inflammation, such as CRP, are prominent predictors of elevated blood pressure, and a few observational studies have confirmed their role in the development of hypertension." (PMID 37298077, 2023). "Patients are more likely to develop coronary sluggish flow if they have risk factors such as (hypertension, smoking, increased BMI, dyslipidemia, high platelet count, high hematocrit value, high NLR, high PLR, and high CRP level)." (PMID 37161453, 2023). "In sum, the main risk factors correlated with metabolic disease and cardiovascular risk were WC, hypertension, atherogenic dyslipidemia (elevated TC, low HDL-C), HDL-C, TGL and inflammatory parameters (CRP, PAI-1)." (PMID 36920931, 2023). "Six prediction factors constitute the prediction model, including hypertension, CRP, SIRI, ACCI, low potassium and anemia, which are easily available in clinical practice." (PMID 37202743, 2023). "On the univariate analysis, hypertension, severe WMLs, large atherosclerotic stroke, homocysteine, and hypersensitive C-reactive protein levels differed significantly with increasing quartiles of CitH3 concentrations." (PMID 37508923, 2023). "Hypertension is an inflammatory disease, and the inflammatory markers C-reactive protein (CRP), various cytokines, and pathway complement pathway products are increased in patients with hypertension." (PMID 36911741, 2023). "Hypertension, CRP, SIRI, ACCI, low potassium and anemia were significant predictors of preoperative atrial fibrillation." (PMID 37202743, 2023). "The association with waist circumference persisted after adjusting for ASCVD and statin use (model 1) but decreased after adjusting for HOMA-IR, adiponectin, C-reactive protein, hypertension status and dyslipidemia status (model 2)." (PMID 37013573, 2023). "In a retrospective study on the Taiwanese population, hypertension was shown to have an inverse effect on vasospasm, especially in females with high C-reactive protein (CRP) levels." (PMID 37342301, 2023). "Consistent with other studies, it was significantly correlated with BMI, hypertension, and systemic inflammatory parameters: CRP, resistin, and PAI-1." (PMID 36920931, 2023). "Our study also found markedly higher rates of chronic and acute renal failure, atherosclerotic heart disease, essential hypertension, and peripheral vascular disease as well as higher mean CRP levels in PAH patients." (PMID 37089865, 2023). "Severalstudies have shown inflammatory markers such as CRP as an independent determinant of endothelium dependent vascular function among patient with coronary heart disease (CHD) in patients with hypertension." (PMID 37654837, 2022). "Inflammatory markers (e.g. C-reactive protein, chemokines and adhesion molecules) are increased in patients with hypertension and predict the development ofcardiovascular disease." (PMID 37654837, 2022). "Blood tests taken within 24 h of admission to hospital showed similar values for C-reactive protein and platelets (all; p > 0.05) whereas white blood cell count was marginally higher and haemoglobin marginally lower in those with pre-existing hypertension." (PMID 35352027, 2022). "our study, as a cross-sectional study, was unable to assess the relationship between CRP concentration and the severity of hypertension, with a small sample size, and further prospective analysis is needed in the future." (PMID 36418968, 2022).
Hypertension (continued). "The DASH diet pattern was already established as a potential treatment for hypertension, to reduce both fasting and postprandial insulin concentrations, and CRP levels." (PMID 35276919, 2022). "The variables predicting severe disease were patient global pain, treatment with synthetic DMARDs, clinical form at diagnosis, high CRP, arterial hypertension, and psoriasis affecting the gluteal cleft and/or perianal area." (PMID 35572968, 2022). "The Kaplan-Meier plot of stroke according to the elevated-CRP levels and hypertension showed the cumulative incidence rates of new-onset stroke." (PMID 36262245, 2022). "Among them, 14 outcomes (all-cause mortality, CVD, MACE, stroke, hypertension, CVD mortality, SBP, BMI, CRP, TC, DM, GDM, GFR, CRC) were found to be significantly associated with TMAO concentrations." (PMID 35348578, 2022). "and the patient's baseline characteristics were collected and compared between the groups, and the correlation between CRP and other factors and hypertension in the elderly was analyzed by multi-factor logistic regression." (PMID 36418968, 2022). "Short sleep increases blood pressure, C-reactive protein, cortisol levels, and sympathetic nervous system activity, which can lead to hypertension and cerebrovascular disease." (PMID 36388217, 2022). "Based on the results of this study, we suggest that BMI, WHR, Hb, and CRP should be the important indicators of early stage hypertension in sub-healthy adults." (PMID 36010315, 2022). "The two cohorts differed on CRP, history of hypertension, symptoms on admission including fever, cough and expectoration." (PMID 36601398, 2022). "In our study, we identified that NIH stroke scale and total SVD burden were independent risk factors for PSD in RSSI patients, after adjusting for age, gender, history of hypertension, C-reactive protein level and fibrinogen level." (PMID 34979972, 2022). "With the filter method for variable selection, we selected the eight important variables as follows: hypertension, age, any comorbidity, aspartate aminotransferase, lactate dehydrogenase, SpO2 at the first visit, pneumonia, and C-reactive protein." (PMID 35280897, 2022). "Only hypertension, the use of angiotensin-converting enzyme inhibitors, PaO2/FiO2, respiratory rate and C-reactive protein were selected for the multivariate analysis." (PMID 35081151, 2022). "Elevated levels of circulating cytokines and C-reactive protein (CRP) marked hypertension as a low-grade inflammatory disease involving innate and adaptive immune responses." (PMID 36035928, 2022). "Several studies investigating inflammation and pathogenetic processes in hypertension have reported higher serum CRP, uric acid, and calcium levels." (PMID 35096423, 2022). "Hierarchical multiple regression models were constructed assessing the relationship between haemoglobin concentration and each cognitive measure and these were corrected for age, sex, education, C-reactive protein, hypertension, and body mass index." (PMID 35251870, 2022). "Third, some individuals were excluded due to incomplete information on CRP concentration and hypertension on the baseline." (PMID 36262245, 2022). "The binding of phosphocholine to C-reactive protein localized the SCTB villi cells has been reported to induce arterial hypertension and placental damage." (PMID 36361721, 2022). "The results revealed that smoking, hypertension and CRP were independent determinants of plaque progression (Model 1)." (PMID 36404308, 2022). "34.9% of the participants had hypertension, 61.5% had hypercholesterolemia, 57.8% had hypertriglyceridemia and 11.9% had inflammation (high levels of CRP or IL-6)." (PMID 34991564, 2022). "Our study demonstrates that screening and monitoring individuals with high CRP levels and hypertension using easy-access tools can be effective in the prevention of stroke." (PMID 36262245, 2022).
Hypertension (continued). "At the age of 40 years, a routine checkup revealed that she had persistently mildly elevated C-reactive protein (CRP) (0.2–0.4 mg/dL) levels and worsening hypertension." (PMID 35432647, 2022). "Age, blood pressure, blood urea nitrogen, creatinine, C-reactive protein, soluble thrombomodulin, pentraxin 3, frequency of hypertension, hematuria, and proteinuria were significantly higher in patients with AAV than in the controls." (PMID 35160215, 2022). "Fourth, considering that the differences in the AUC between adding elevated-CRP levels and hypertension to the conventional model were relatively small." (PMID 36262245, 2022). "In this study, periodontitis patients with hypertension showed obviously higher hs-CRP and IL-6 levels compared with patients with periodontitis alone (P < 0.05)." (PMID 35813436, 2022). "Prediction models for the dynamic and control of COVID-19 infection found broad similarities with the features retained in our models, particularly regarding aging, hypertension, CRP, LDH, prothrombin, lactate, and neutrophil levels." (PMID 35677769, 2022). "The clinical characteristics including age, sex, drinking behavior, history of hypertension, body mass index, waist circumference, total cholesterol, fast plasma glucose, urea, serum creatinine, C-reactive protein, and SUA were recorded." (PMID 35600604, 2022). "Compared with the conventional model (AUC = 0.7388), after elevated-CRP levels and hypertension are added to the conventional model, the discrimination and risk reclassification ability can be significantly improved." (PMID 36262245, 2022). "The prevalence of hypertension, coronary artery disease and joint reactive inflammation was significantly higher in the group with elevated CRP." (PMID 36418968, 2022). "Except four risk factors including age, hypertension, WBC, and CRP found in the logistic regression model, a new risk factor, PLT, was found in the XGBoost model." (PMID 35559036, 2022). "When we restricted meta-analyses to only include cohort studies, 11 outcomes (all-cause mortality, MACE, hypertension, CVD mortality, SBP, CRP, HDL cholesterol, LDL cholesterol, TC, DM, GFR) were still significantly associated with TMAO concentrations." (PMID 35348578, 2022). "The feature importance and SHAP value of XGBoost indicated that age, hypertension, platelet count (PLT), C-reactive protein (CRP), and white blood cell count (WBC) were risk factors of HF." (PMID 35559036, 2022). "The significant indirect effect of periodontal infection on hypertension mediated through CRP was determined via two national databases." (PMID 35935796, 2022). "There was a significant difference between the groups in respect of medical history of hypertension (p = 0.005), CRP (p < 0.001), homocysteine (p = 0.002), fibrinogen (p = 0.016), and proteinuria (p = 0.01)." (PMID 35369646, 2022). "Other riskfactors, including hypertension, C-reactive protein (CRP), urea, glucose,D-dimer, activated partial thromboplastin time (APTT), and procalcitonin, whoseP values were less than .05 were subsequently selected foradjustment." (PMID 34550036, 2022). "The patients with hypertension, ischemic heart disease and type 2 diabetes showed higher suPAR and CRP concentrations at the baseline as well as on subsequent days of hospitalisation." (PMID 35330458, 2022). "The value of AUC was 0.7636, the value of NRI was 0.3499 (P < 0.0001), and the value of IDI was 0.0052 (P = 0.0026) for those with elevated-CRP levels and hypertension." (PMID 36262245, 2022). "In the multivariate analysis, the variables gender, age, BMI, LDL-C, HDL-C, SBP, DBP, TyG index, Cr, SUA, eGFR, BNP, CRP, history of smoking, hypertension, and hyperlipemia were adjusted." (PMID 35295991, 2022). "A score for prediction of acute myocarditis was calculated using six parameters [age, previous infection, hyperlipidemia, hypertension, C-reactive protein (CRP), and leukocyte count]." (PMID 35755032, 2022).
Hypertension (continued). "Cardiovascular measures included cardiometabolic biomarkers such as C-reactive protein (CRP), hypertension/blood pressure, and having either a history of or dying from heart disease." (PMID 34997433, 2022). "Our results showed a significant correlation between FAR and AHI, i.e., severity of OSA, BMI, CRP and hypertension." (PMID 36294433, 2022). "Over the past several decades, stroke has become a leading cause of mortality and disability worldwide and there are substantial economic costs for post-stroke care, and 13.8% of participants with hypertension have elevated-CRP levels in CHARLS." (PMID 36262245, 2022). "we found that the proportion of hypertension, coronary heart disease and arthritis in patients with elevated CRP was significantly higher than that in patients with normal CRP." (PMID 36418968, 2022). "Our study found that CRP, as a marker of systemic inflammation, was significantly positively correlated with hypertension in the elderly." (PMID 36418968, 2022). "On account of linkage disequilibrium (LD) and confounding factors (BMI, LDL, T2D, TC, TG, cigarette and alcohol consumption, hypertension, and CRP), 10 SNPs were excluded." (PMID 36119739, 2022). "LASSO regression analysis identified six of these at λ1SE as associated with the highest or least probability of myocarditis (age, previous infection, hyperlipidemia, hypertension, CRP, and leukocyte count)." (PMID 35755032, 2022). "Strong predictors after screening included BMI, educational level, family heart disease, family hypertension, family allergies, high myopia, other illness, other drugs taken, stress, CRP, BCVA, and spherical equivalent." (PMID 35566498, 2022). "We conducted a series of sensitivity analyses, there was a robust combined effect of elevated-CRP levels and hypertension on new-onset stroke." (PMID 36262245, 2022). "The reported prevalence of hypertension in our patients was high (62%) and possibly related to the systemic inflammation in RA and moderately increased CRP levels (mean 2.9 mg/dL)." (PMID 36128215, 2022). "Compared to females, males with essential hypertension complicated by HFpEF display significantly higher blood levels of pro-inflammatory autacoids: C-reactive protein, tumor necrosis factor alpha, and interleukin-6." (PMID 35997392, 2022). "In the high-risk group, there are 76.9% of the respondents with high cholesterol, also 46.2% of the respondents with high blood pressure, and 69.2% of the respondents with high CRP." (PMID 35628058, 2022). "Although the blood pressure was comparable between the two groups, it is evident that hypertension was more prevalent in patients with T2D and high CRP levels." (PMID 35844722, 2021). "Compared with control group, the mean of C-reactive protein (CRP) levels, the rates for hypertension and T2DM of case group are significantly different (all p < 0.05)." (PMID 33407151, 2021). "In univariate analysis, old age, male sex, BMI ≥ 25 kg/m2, hypertension, cardiovascular disease, DM, CRP level, LDH level, creatinine level, and ferritin level were significantly associated with disease progression." (PMID 34419004, 2021). "The multivariable analysis showed that wound ischemia, age, CRP, and hypertension medication use retained significance." (PMID 33996886, 2021). "The associations were independent of age, gender, marriage status, education level, place of residence, smoking behavior, alcoholic intake, BMI, hypertension, fasting plasma glucose, total cholesterol and CRP." (PMID 33686964, 2021). "Obese women (BMI >31 kg/m2) accounted for 70% of repeated elevations; female sex, lower income, Black race, and hypertension were each independent predictors of persistent CRP level above 10 mg/L." (PMID 33869996, 2021). "Age, rural area, falls, higher C-reactive protein (CRP), and chronic diseases (including hypertension, chronic lung diseases, heart disease, psychiatric disease and arthritis) were associated with a higher risk of possible sarcopenia." (PMID 33661964, 2021).